IL10 (interleukin 10)
Diseases named in the same sentence as IL10 in open-access papers (continued):
Sharing a sentence is not in itself a finding about the gene and the disease.
tumor (continued). "C5aR can also facilitate tumor metastasis by suppressing the response of CD4+ and CD8+ T cells in the lung, possibly driven by the recruitment of immature myeloid cells to the lungs and the production of large amounts of TGF-β and IL10." (PMID 34688269, 2021). "Thus far, many obstacles impaired the success of vaccines in cancer therapy such as the action of immunosuppressive Tregs, the high release of immunosuppressive cytokines, such as IL10, TGFβ, IL2, and of T-cell checkpoint ligands in the tumour milieu." (PMID 34204326, 2021). "Furthermore, Plasmodium immunotherapy inhibits tumor secretion of cytokines and chemokines that could recruit MDSCs, Tregs and other immune suppressor cells into tumor, therefore reduces the numbers of these cells, and decreases the level of their effector molecules (such as IL-10 and TGF-β)." (PMID 34243757, 2021). "Our data demonstrate that vvDD-IL-23 treatment can deliver IL-23, not IL-23A to the tumor bed and elevate IL-10 expression and, in turn, prolong viral persistence and IL-23 accumulation." (PMID 34093846, 2021). "Within the tumor microenvironment, GAM are forced to transform to M2 phenotypes by GBM cells that secrete factors such as IL-10, IL-4, IL-6, macrophage colony-stimulating factor, macrophage inhibitory factor, TGFβ, and prostaglandin E2, which subsequently supports tumor growth and invasion." (PMID 34267749, 2021). "IL10/STAT3 also promotes tumor proliferation and tumor metastasis via immunosuppression." (PMID 33500726, 2021). "This experiment evaluated the effects of combination therapy and single therapy based on cytokine secretion using ELISA to quantify IFN-γ, TNF-α, IL-2, and IL-10 which is a negative immunoregulatory factor, in tumor tissues." (PMID 33792840, 2021). "Indeed, the poor activation of pDC in the TME and their active instruction by tumor cells lead to an immunosuppressive function through the production of IDO, IL-10, or OX40." (PMID 33418996, 2021). "For Treg cells, APS might inhibit the tumor growth partly by decreasing Treg with a lower TGF-β and IL-10 mRNA expression in the spleen." (PMID 34721026, 2021). "This mismatch between CSF IL-10 decrease and CT scan findings hints that CSF IL-10 is not generated exclusively by tumor cells." (PMID 33618687, 2021). "Exclusion of the IL-10 inducing citCp450 peptide from the combined vaccine failed to recover a strong anti-tumour response." (PMID 34858415, 2021). "The upregulated levels of STAU2 protein only in T and B cells might be related to the RNA transport mechanism to produce various inflammatory cytokine (IL-10, TNF-α) molecules that are required to promote tumour growth in the cancer microenvironment." (PMID 33441653, 2021). "Interestingly, secretion of IL-10 and TGF-β by tumor-infiltrating M2 macrophage can stimulate the immunosuppressive activity of Tregs." (PMID 33809137, 2021). "We found that the levels of IL-10 and PGE2 in tumor tissues in the CUMS group were significantly higher compared with those in the control group, suggesting that CUMS could reduce the immune function to a lower level." (PMID 34422050, 2021). "Confirming TBK1 vs. IKKα/β dichotomy of mRIPO vs. LPS treatment, tumor homogenate cytokine analysis revealed stronger IKKα/β-driven cytokine induction by LPS (IL-6, TNF, IL-1β, IL-10), with CXCL10 (TBK1-dependent) being the most prominently induced cytokine after mRIPO treatment." (PMID 33767151, 2021). "Here, TAM primarily serves to promote tumor growth and progression via the generation of angiogenetic factors such as vascular endothelial growth factor (VEGF), and the secretion of immunomodulatory cytokines (e.g., IL-6, IL8 and IL-10)." (PMID 33430105, 2021). "Upon overproduction, IL-10 may impair the immune response by inhibiting the production of IL-2, IFN-γ, and IL-12, which are essential for virus and tumor cell clearance." (PMID 33750983, 2021).
tumor (continued). "Furthermore, dendritic cells exposed to MUC2 produce less TNFα and IL-12, as well as more IL-10 and TGFβ1 in the large intestine, which suggests that MUC2 can deliver immunoregulatory signals to support tumor growth and treatment resistance." (PMID 34300195, 2021). "Apoptotic tumor cells can express a large amount of calreticulin (CRT) on the surface of DCs and release HSPs and HMGB1, which can effectively fight against IL-10 or TGF-β, which have a negative regulatory effect." (PMID 34588987, 2021). "Furthermore, M2 polarization is characterized by the expression of surface CD163 and CD204, expression of intracellular STAT-3 and the production of arginase, IL-10, and transforming growth factor beta 1 (TGF-β1), supporting tumor invasion and angiogenesis." (PMID 33917013, 2021). "In addition to recruitment of natural Treg to the tumor stroma, TAMs are also involved in the induction of Treg cells in the TME through regulation of Foxp3 via IL-10 and TGF-β signaling." (PMID 34771482, 2021). "Tumor cells can release a large number of cytokines in the process of immune remodeling, such as IL-10 and TGF-β, the latter can weaken the killing activity of cytotoxic T lymphocytes and natural killer cells, evading immune surveillance and promote tumor metastasis." (PMID 33967748, 2021). "Other cytokines (CCL2, IFNγ, IL-12, IL-10, TNFα, IL-4, and IL-1β) evaluated were not significantly changed, suggesting that additional unidentified tumor-derived soluble factors promote alternative activation in BMDMs." (PMID 35008514, 2021). "This can be seen by the reduced secretion of typical inflammatory cytokines such as IL-6, IL-12, IL-2, IFN-γ, TNF-α, IL-8, GM-CSF, and IL-1β and the increase in production of IL-4, IL-10, and PGE2, which are commonly considered drivers of a tumor-promoting microenvironment." (PMID 33804027, 2021). "In addition, overexpression of SPON2 enhanced, while knockdown of SPON2 reduced IL10, CCL2 and CSF1 expression levels and secretion in CRC tumor cells." (PMID 34583750, 2021). "We observed significant negative correlations between CD68+ macrophage infiltrations in the tumor tissue and the concentrations of the cytokines eotaxin, IFN-γ, IL-1β, IL-2, IL-10, IL-13, IL-16, VEGF and factor score of component 2 (“Inflammatory Cluster”) in the CSF." (PMID 34654395, 2021). "Moreover, the positive correlation between FOXD1 expression and immunosuppressive genes, such as PD-L1, IL-10, TGFB1 and TGFBR1, indicate the key role of FOXD1 in regulating tumor immunology." (PMID 34028536, 2021). "Tumor cells (1 × 105 cells/ml) were incubated in a medium with or without MJ (2.5 mM) for 18 h followed by estimation of IL-10, VEGF, and TGF-β in the culture supernatant by ELISA as described in the materials and methods." (PMID 33716751, 2021). "SPON2 may indirectly induce M2-polarization through upregulating cytokines including IL10, CCL2 and CSF1 expression in tumor cells." (PMID 34583750, 2021). "MDSCs accumulate to almost all tumor types and create an immunosuppressive tumor microenvironment by secreting factors such as arginase I, inducible nitric oxidate synthase (iNOS), TGF-β and IL-10, as well as other immunosuppressive factors." (PMID 34204474, 2021). "Additionally, immunosuppressive molecules such as IL-10 and TGF-β accumulate in ECM rich tumor partly due to low diffusion and buildup of hypoxic and metabolic stress." (PMID 33828127, 2021). "Univariate analyses revealed that the baseline bone marrow tumor burden, CRS severity, several serum biomarkers (including max lg CRP, IL-10, IFNγ, ferritin, and D-dimer levels), and the usage of tocilizumab/corticosteroids were statistically associated with the incidence of severe cytopenia." (PMID 34277448, 2021). "Furthermore, it has been reported that CCL2, IL10, and CSF1 not only expressed in tumor cells, but also in macrophages." (PMID 34583750, 2021).
tumor (continued). "For instance, tumour ECs are capable of boosting the level of Fas ligand (FasL) and thereby selectively kill effector CD8+ T cells in the presence of tumour-derived VEGF, prostaglandin E2 and IL-10 stimulation." (PMID 33917287, 2021). "Mature DCs loaded with PAM lysates showed an increased maturation potential, as estimated by their increased expression of CD83, CD86, CD40, IL-12/IL-10 production, and attenuated PDL1 and ILT-4 expression, compared to the DCs treated with control tumor lysates." (PMID 33915703, 2021). "The expression of two additional M2-related markers, ARGINASE1 (ARG) and INTERLEUKINE10 (IL10), was measured to further evaluate if the reduction of FOXE1 levels could affect the abundance of this macrophage subpopulation within the tumour." (PMID 34299284, 2021). "Finally, M2cM2d and other malignant hybrids would be spatially constrained into a hypoxic area, behaving as regulators secreting IL-10 and TGF-β, creating a tumor proliferation scenario progression." (PMID 34177892, 2021). "IL-10 upregulates the expression of AID and triggers the induction of SHM and CSR from IgM to IgA, which may mediate tumor progression." (PMID 34868013, 2021). "ATRA decreased the expression of immunosuppressive genes through the downregulation of TGF-β, PD-L1, IL-10, and IDO in MDSCs and upregulated MHC class I homologs MICA and MICB on tumor cells, enhancing NK cell activity and cytotoxicity of T cells in the CD8− and CD4− immune response." (PMID 34025641, 2021). "The liver region has high concentrations of immunosuppressive cytokines, such as IL-10, which inhibit CTLs to secrete IFN-γ that may affect the ability of CTLs to kill tumor cells." (PMID 33391470, 2021). "After therapeutic period, Andro could remarkably reduce IL-6, IL-1β, TNF-α, VEGF, MMP-2 level in blood and IL-10, TGF-β, NF-κB level of tumor tissue with significantly statistical implications (p < 0.01)." (PMID 33967748, 2021). "In support of this hypothesis, we found large necrotic areas within the tumor and high amount of the inflammatory cytokines MCP-1 and IL6 and of immunosuppressive cytokine IL10." (PMID 34604232, 2021). "In contrast to the tumor lysates commonly used in DC vaccines, PAM-tumor lysates lacked the capacity to increase IL-10 production by DCs, and their potential to induce protumorogenic Th2 and regulatory T cells." (PMID 33915703, 2021). "In contrast, IL-10 and TGF-β levels increased when animals were drinking DSS-containing water compared to the control, but were further enhanced in the intervals between DSS consumption, with the exception of TGF-β at the tumor stage." (PMID 34675913, 2021). "Moreover, a variety of tumor immune-related cytokines such as IFN-γ, TNF-α, TGF-β, IL10, and IL4 were notably increased in cells after upregulating the expression of miRNA-542-3p in HepG2 and Huh7 cells and co-cultured with T cells." (PMID 34988028, 2021). "With IL10 and IL4 secreted by tumor cells and macrophages, respectively, induced M2 polarization." (PMID 34447383, 2021). "Tregs suppress the anti-tumor immune response directly via expression of immunosuppression inducing ligands, such as PD-L1 and CTLA-4, or indirectly via the release of anti-inflammatory cytokines, including IL-10 and TGF-β." (PMID 34084145, 2021). "IL-10 is an inhibitor of tumor immune response and has a direct negative effect on the expression of NF kappa B. It is expressed mostly in monocytes and Th2 lymphocytes." (PMID 34204596, 2021). "Besides IL-10, TGF-β, and IFN-γ, it is the concerted action of multiple cytokines within the TME that mainly determines the extent and success of anti-tumor immune responses." (PMID 33669271, 2021). "However, tumor cells and regulatory T cells (Tregs) suppress the killing effect of CTLs by secreting IL-10 and TGF-β, thus realizing tumor immune escape." (PMID 34692496, 2021).
tumor (continued). "Following differentiation, Th2 cells can produce IL-4, IL-5, IL-10, IL-13, and IL-17, not all of which are beneficial in cancer and contribute to tumor growth and metastasis." (PMID 35087869, 2021). "However, within the TME, they inhibit anti-tumor immunity through multiple mechanisms including via CTLA-4 and the production of immunosuppressive cytokines TGF-β and IL-10." (PMID 34831452, 2021). "Even in an alternative scenario with increased TFR numbers, DLBCL cells might also be able to take advantage of IL-10 locally produced by these cells, demonstrating a complex role of TFR cells within the tumour microenvironment of DLBCL." (PMID 34572910, 2021). "It is likely that IL-10 is a chemoattractant for CD8+ T cells and the oncolytic Ad5-hTERT could improve the production of CD8+ T cells in the tumor microenvironment." (PMID 33717103, 2021). "TGFB1, IL1B, IL10, IL6, PTGS2, and PPARG closely interacted with the tumor microenvironment." (PMID 34394377, 2021). "Furthermore, STAT3 has been shown to mediate immunosuppressive effects in the TME via production of IL-10 and TGF-β, supporting tumour growth whilst reducing anti-tumour immunity." (PMID 33546207, 2021). "There was evidence that all cytokines investigated, in relation to GC, have pro-tumour effects, although TNF, IFN-γ, and IL-10 may also participate in anti-tumour processes." (PMID 34944729, 2021). "We previously demonstrated that the OC tumor endothelium acted as a potent immune barrier by expressing the death mediator Fas ligand (FasL/CD95L) that preferentially killed CD8+ T cells, and such FasL expression was cooperatively induced by tumor-derived VEGF, IL-10, and PGE219." (PMID 33723260, 2021). "In addition to tumor cells, these cells facilitate tumor growth and proliferation by producing growth factors, local cytokines, and chemokines in solid tumors, including VEGF and IL-4, IL-10, and TGFβ." (PMID 33494834, 2021). "Another study revealed that let-7b delivery could reactivate tumor-infiltrating DCs by acting as a TLR-7 agonist and suppressing IL-10 production in vitro." (PMID 34359591, 2021). "Although both tumors and the surrounding hepatic tumor was infiltrated with a higher level of IL10 than normal liver tissues, the difference of IL10 level in tumor and its surrounding hepatic tissues is not significant." (PMID 33633112, 2021). "Importantly, the positive correlations between FUCA2 expression and immunosuppressive genes, such as TGFB1, PD-L1, and IL10, further affirming the key role played by FUCA2 in regulation of tumor immunology, and macrophage polarization." (PMID 34745134, 2021). "E. coli NC101Δpks, which does not produce colibactin, exerted lower tumor-promoting effects than E. coli NC101 in AOM-treated Il10−/− mice." (PMID 33578830, 2021). "Effector T-cell infiltration into the tumour is hindered through the upregulation of VEGF to promote dysregulated angiogenesis, and via the downregulation of integrins (αLβ2) on vascular endothelium by upregulating IL-10 production." (PMID 33923305, 2021). "The potential mechanisms that may be involved in Treg generation involve other mediators, such as TGF-β, IL-10, and IDO, and interactions with tolerogenic DCs or stromal cells in the tumor milieu." (PMID 34026621, 2021). "However, in advanced HCC, macrophages express M2-like molecules, including macrophage mannose receptor c1, arginase, IL-10, and transforming growth factor-β and low levels of MHC-class II, which promote tumor progression." (PMID 33854960, 2021). "Subsequently, the tumor cell microenvironment was filled with abundant growth factors and inflammatory mediators [colony stimulating factor-1 (CSF-1), IL-4, IL-10, and TGF-β], which changed the phenotype of macrophages into M2-type macrophages with the function of promoting tumor growth." (PMID 34950700, 2021).
tumor (continued). "TAMs can promote the growth and survival of cancer cells and suppress the anti-tumour immune response through expression of arginase 1 (ARG1), inducible nitric oxide synthase (iNOS), IL-10, transforming growth factor β (TGFβ), and indoleamine 2,3 dioxygenase (IDO)." (PMID 34885021, 2021). "Furthermore, its combination with HSP70 vaccine induced a potent anti-tumor immunity by increasing the expression of Th1 cytokines, IL-2, and IFN-γ and decreasing transcription levels of IL-10, TGF-β, and Foxp3 in the tumor microenvironment." (PMID 34531847, 2021). "Besides, CTLA-4 contributes to the development of the immunosuppressive tumor microenvironment in HCC via promoting Treg, IDO, and IL-10 production in the DCs." (PMID 34947886, 2021). "The increased IFNG response together with IL4, IL10, VEGF, TGF-beta and immune checkpoints comprise the tumor microenvironment that dominating the immune response, making artificial manipulation of one component only transiently alter the equilibrium reached by such biological response network." (PMID 34566988, 2021). "The production of soluble factors such as IL‐10 and TGF‐β, and metabolic mediators prostaglandin E2 (PGE2), indoleamine 2,3‐dioxygenase (IDO) and arginase can impair activation and cytotoxicity or push responses towards tumour‐promoting TH2 and TH17 responses." (PMID 32741067, 2021). "However, the pivotal role of DC in cancer immunity has two distinct sides, since DC function can also be exploited by the tumor to inhibit immune effectors in the TME, either via checkpoint ligands like PD-1 or soluble factors like IL-10." (PMID 33804027, 2021). "What we do know is that in the absence of pro-inflammatory cytokines such as IL-1β, TNF-α, and GM-CSF, paracrine IL-10 debilitates the early influx of PMNs and permits initial tumor formation by transitorily paralyzing a prompt non-specific antitumor response." (PMID 35003081, 2021). "Furthermore, IL-10 and IL-35 derived from Treg cells promote the exhaustion of CD8+ tumor-infiltrating lymphocytes." (PMID 34885241, 2021). "In addition, atovaquone suppressed MDSCs and Tregs in blood and tumor cells with a reduction in immunosuppressive cytokines TGF-β, IL-10 and RPS19." (PMID 34068008, 2021). "Moreover, IL-10 has pro-tumor activity in TME, and IL-10 facilitated Tregs and M2-like macrophages development, as well as counteracting CD4+ T cells, cytotoxic CD8+ T cells and NKs tumoricidal function." (PMID 33957948, 2021). "Following differentiation, TH2 cells secrete IL-4, IL-5, IL-10, IL-13, and IL-17, not all of which are beneficial in cancer and have been shown to contribute to the tumor promoting role of this subtype." (PMID 34012451, 2021). "Tumour cells and TAMs also exhibited increased Nos2, IL-12b, and IFN-γ expression with a concomitant reduction in the expression of the M2- Mφ markers arg1, IL-10, TGF-β." (PMID 34249942, 2021). "Interestingly, in metastatic breast cancer, regulatory T cells can originate from the CD4+ T cells as a result of stimulation by the immunosuppressive cytokines such as IL-10 and TGF-β secreted by tumor-evoked B cells." (PMID 34885122, 2021). "FasL expression was induced by tumour-derived VEGFA, IL-10 and prostaglandin E2 (PGE2)." (PMID 34885021, 2021). "However, the alternatively activated microglia/macrophages promote tumor survival by producing anti-inflammatory cytokines such as IL-4, transforming growth factor-beta (TGF-β), and IL-10, defined as M2 markers." (PMID 34267749, 2021). "IL-10 cooperates with other not yet identified tumor-derived soluble factors to promote TAM development." (PMID 33917598, 2021).